RYBP (RING1 and YY1 binding protein)
Diseases named in the same sentence as RYBP in open-access papers (continued):
Sharing a sentence is not in itself a finding about the gene and the disease.
infection (continued). "Importantly, we found that the 3xFLAG-RYBP mutant that lacks only the 14-aa RBD still binds to KSHV lytic promoters during de novo infection as efficiently as WT RYBP, which confirms that the interaction of RYBP with PRC1 is not required for its binding to KSHV promoters." (PMID 36026503, 2022). "To determine whether RYBP affects the formation of KSHV epigenome during de novo infection, we infected shControl- and shRYBP-treated SLK cells with RTA-KO KSHV and performed a FAIRE assay and ChIPs for different epigenetic factors on viral promoters at 24 hpi." (PMID 36026503, 2022). "Taken together, these data indicate that RYBP can restrict the KSHV lytic cycle as early as 4 hpi, and that it is required for blocking KSHV lytic replication following de novo infection." (PMID 36026503, 2022). "Thus, we confirmed that RYBP can function as a PRC1 factor on host promoters, but our results imply that RYBP functions differently on KSHV promoters during de novo infection." (PMID 36026503, 2022). "However, by 6 h after infection, PGRP-LB expression had returned to near normal in both males and females, while RYBP expression was now induced in males to the same high level seen from 1 h in females." (PMID 34341118, 2021). "We found that, during de novo infection, the binding of RYBP on the viral genome precedes that of EZH2, indicating a sequential recruitment of PcG proteins, where RYBP may recruit PRC1 independently of PRC2 at specific lytic promoters." (PMID 24367262, 2013). "We found that RYBP, a main subunit of the non-canonical PRC1 complexes, is a potent repressor of KSHV lytic genes that can bind to the viral genome and inhibit lytic genes as early as 4 hours post infection." (PMID 36026503, 2022).
RYBP also shares sentences with these, for which no sentence is quoted: glioblastoma (2 papers); adult T-cell leukemia (1); anaplastic thyroid cancer (1); B cell lymphoma (1); diabetes (1); heart failure (1); heart transplant (1); Hepatic steatosis (1); lung adenocarcinoma (1); lymphoma (1); nematode infection (1); neurological disorder (1); non-small cell lung carcinoma (1); Obesity (1); pancreatic ductal adenocarcinoma (1); preeclampsia (1); uterine corpus endometrial carcinoma (1).